IL2 (interleukin 2)
Diseases named in the same sentence as IL2 in open-access papers (continued):
Sharing a sentence is not in itself a finding about the gene and the disease.
Sepsis (continued). "According to previous research, narcolepsy patients tend to secrete higher levels of cytokines, including IL-2, tumor necrosis factor, IL-4, and IL-13, which could be the reason for narcolepsy being a protective factor against severe sepsis and 28-day mortality in sepsis patients." (PMID 38343642, 2024). "To address if sepsis alters the bystander/innate function of naïve CD8 T cells, we stimulated splenocytes derived from Sham- or CLP-treated mice with IL-12/IL-18 ± IL-2 or PMA/ionomycin for 5 hours." (PMID 37824591, 2023). "To mimic the inflammatory environment of sepsis, we added LPS, IFN-γ, and IL-2 during the 2-day isolated monocyte culture." (PMID 37592321, 2023). "When monocytes were challenged with LPS, IL-2, and IFN-γ to simulate sepsis, monocytes that had efferocytosed viable MSC had higher levels of IDO while monocytes that efferocytosed heat inactivated-MSCs produced the lowest levels of TNF-α." (PMID 37592321, 2023). "Patients in the sepsis group had higher PCT, WBC, CRP, IL-1β, IL-2, IL-6, IL-8, IL-10, IL-12, IL-17, IFN-γ, and SOFA scores than those in the infection group, and the difference was statistically significant (P < 0.05)." (PMID 35937269, 2022). "Corticosteroids are appealing agents due to their broad anti-inflammatory effects against cytokines such as Interleukin (IL)-1, IL-2, Tumor Necrosis Factor (TNF)-α, and IFN-gamma, which can lead to sepsis and respiratory failure." (PMID 35991665, 2022). "Rs12196996 GG and rs2232365 AA were also correlated with increased level of miR-23a, IL-10 and decreased level of TNF, IL-2, IFN, IL-6 and IL-1β in the peripheral blood cell samples of patients with ICU-acquired sepsis." (PMID 35156517, 2022). "Among them, BCHE, AKT1, and IL2 are involved in the sepsis pathway, and LGALS3 is involved in both the sepsis and glycocalyx pathways." (PMID 36062176, 2022). "Our results showed that sepsis increased the production of inflammatory cytokines TNF-α, IL-2 and IFN-γ, which was ameliorated by pretreatment with L. rhamnosus TR08." (PMID 34536996, 2021). "ELISA showed that the levels of TNF-α, IL-2 and IFN-γ were significantly higher in sepsis group compared with control group (P < 0.05)." (PMID 34536996, 2021). "Significant differences were observed in the expression of the pro-inflammatory cytokine genes IL-2, IL-6, TNF, and IFN-γ and the anti-inflammatory cytokine genes IL-4 and IL-10 between sepsis patients and healthy controls." (PMID 32922168, 2020). "Other biomarkers that can indicate the immune state in sepsis patients include apoptosis markers (Bim, Bid and Bac), caspases, leukocyte markers (HLA-DR, PD-1, FOXP3, CD127) and cytokines (IL-2, IL-6, IL-12, IL-17, IL-22, IL-33, TNF-α, IFN-γ, IL-10 and TGF-β)." (PMID 33336293, 2020). "Studies have observed a decrease in the production IL-2, IL-12 and IFN-γ from both Th1 and Th2 populations in sepsis patients, and these cells persist in displaying significant reductions in their secretory profiles in sepsis survivors." (PMID 33336293, 2020). "While IL-2, CXCL10, and TNF-α contribute to the pathogenesis of sepsis, IL-7, IL-10, GCSF, MCP1, M1P1A are likely elevated as an endogenous attempt to combat sepsis." (PMID 32973504, 2020). "Comparison of molecules between the control and sepsis groups revealed statistically significant differences, except for IFN-α, IL-1RA, IL-1β, IL-2, IL-6, IL-7, IL-15, LIF, GM-CSF, TNF-α, CCL4, CCL5, and CXCL12." (PMID 31583025, 2019). "IL-2 expression and release in CD4+ T cells was reduced under sepsis exposure, and this was reversed by inhibiting central HMGB1, especially at the dose of 10 μg BoxA." (PMID 30881224, 2019). "Overall, our study shows that there is an “immunoparalysis” in severe leptospirosis and sepsis: low quantity of NK and TCD4+ cells, low expression of IFN-γ, IL-12, IL-6, IL-1 and IL-2 and high expression of IL-10." (PMID 31114579, 2019).
Sepsis (continued). "CD43-/- septic mice exhibited a decrease in the frequency of IL-2+ CXCR3+ CD4+ cells relative to CD43-/- sham controls, suggesting a sepsis- related shift away from a Th1 phenotype." (PMID 30226896, 2018). "Consistent with previous studies, IL-6 was significantly upregulated in the plasma samples from sepsis patients, as well as in the BAL fluid samples, while minimal and insignificant detection of IL-2 and IL-4 was observed." (PMID 28287491, 2017). "Subsequent elevation of the genes encoding the inflammatory chemokines such as CCL16, CCL25 and CXCL6, and cytokines such as IL-2, IL-8 and IFNG in concert with delayed activation of the coagulation system are the typical signatures of sepsis." (PMID 27003632, 2016). "Many other cytokines (for example, IL-2, IL-12, IL-15, and TNF) can boost the immune system and are reported to be beneficial in murine sepsis models." (PMID 24886820, 2014). "Within 24 h after diagnosis of severe sepsis, peripheral blood mononuclear cells were stimulated ex vivo to measure expression of the activation maker CD25 in T cells, IL-2 levels in the supernatant, and proliferation." (PMID 24962182, 2014). "In the present study we demonstrated that mice with disruption of Atg7 in T cells exhibited a reduced cytokine production of IL-2, IFN-γ, IL-4, IL-10 and IL-17 by CD4+ T cells after sepsis, compared to septic wild-type mice." (PMID 25029098, 2014). "When patients with infection and patients with severe sepsis on ICU admission were compared, IL2, IL7, IL23, IFNγ, and TNFα gene expression was lower in patients with sepsis, while IL-27 gene expression was similar in these two groups." (PMID 23935244, 2013). "The presence of interleukin (IL)‐2, IL‐4, IL‐5, IL‐6, IL‐8, IL‐10, TNF‐α and interferon‐γ was significantly more evident in all three cell culture media transfected with plasma from sepsis patients than in controls, indicating that the transfected cells potentially underwent necroptosis." (PMID 40318009, 2025). "Simultaneously, PD-1 expression was significantly upregulated, and IL-2 and IFN-γ secretion levels were significantly decreased, suggesting that certain components in sepsis patient serum may promote the functional exhaustion of CD4+ T cells." (PMID 41306770, 2025). "9-Hydroxystearate also exhibited a protective role against sepsis, mediated through its positive association with FGF-19 and negative association with IL-2, contributing 9.436% and 12.565%, respectively, to its protective effect." (PMID 39205680, 2024). "In addition, we simulated sepsis using a cocktail of LPS, IFN-γ, and IL-2, whereas the prior studies used LPS alone." (PMID 37592321, 2023). "Interleukin-6, interleukin-2, interleukin-4 and procalcitonin in KD with severe sepsis group were significantly higher than those in KD with non-severe sepsis group." (PMID 37234775, 2023). "Researchers have observed significantly higher IL2 levels in the testes of LPS sepsis rats compared to the normal control group." (PMID 37589002, 2023). "Similar to IL-10-stimulated cells, neutrophils stimulated by LPS or primed by TNF-α in vitro, as well as from the patients with sepsis or NMOSD, also released VEGF, but with a different pattern of chemokines (IL-8, CCL4, CCL5) and cytokines (IL-2, -5, -9, -15, -17, TNF-α) promoting inflammation." (PMID 35757755, 2022). "IL-2, IL-6, IL-10, and NLR were significant after univariate regression analysis, but they were not independent risk factors for sepsis in our study." (PMID 32802049, 2020). "For the proinflammatory cytokines, the levels of IL-1β, IL-2, IL-6, and TNF-α were elevated in the early sepsis phase (2 h), but most other proinflammatory cytokines, including IL-12, IL-15, IL-17, and IFN-γ, showed significant elevation in the late sepsis phase (24–48 h)." (PMID 31354717, 2019).
Sepsis (continued). "Of note, pre-treatment with Rhodiola rosea extract led to further increases in Th1 cytokines (IFNγ, IL-2 and IL-12; all P<0.05), while Th2 cytokine levels were not significantly altered compared with those in the model (sepsis) group." (PMID 26063084, 2015). "The area under ROC curve (AUC) of cytokines, such as IL-2, IL-6 and IL-10 were 0.901, 0.86, 0.888, respectively, which was employed to rule out the diseases of sepsis and intracranial infection." (PMID 24887408, 2014). "In agreement with the activation marker and proliferation data, T-cells from animals with SIRS or sepsis were not impaired in the generation and release of IL-2 in response to soluble CD3 plus CD28 mAb." (PMID 25541945, 2014). "The performances of IL-2, IL-6 and IL-10 to rule out the possibility of sepsis and intracranial infection are comparable with the role of CRP." (PMID 24887408, 2014). "The AUCs for IL-2, IL-6, and IL-10 to rule out the possibility of sepsis and intracranial infection were bigger than CRP." (PMID 24887408, 2014). "No significant changes were observed in IL-1β, IL-2, IL-4, IL-13, GM-CSF, FGFbasic or GM-CSF in caPI3K Tg mice in the presence or absence of sepsis (data not shown)." (PMID 23028587, 2012). "Notably, the IL-2/IL-4 ratio on day +7 in patients with aGVHD showed minimal change, regardless of sepsis presence." (PMID 40718494, 2025). "The lipopolysaccharide infusion induced sepsis-like inflammation with tachycardia, elevated pulmonary pressure, elevated lactate level, as well as elevated pro-inflammatory cytokines like interferon (IFN)-γ, interleukin (IL)-1β, IL-2, IL-6, IL-8, IL-12 and tumor necrosis factor alpha (TNF-α)." (PMID 39273234, 2024). "In addition, PLX-R18 administration attenuated biomarkers of bone marrow aplasia, sepsis, and systemic inflammation and attenuated radiation-induced inflammatory cytokines/chemokines and growth factors, including G-CSF, MIP-1a, MIP-1b, IL-2, IL-6 and MCP-1, and modulate AKT protein expression." (PMID 36292639, 2022). "Also, IL-2 and IFN-γ expressions are reported to be enhanced in the patients with sepsis." (PMID 35992658, 2022). "However, the injection of BoxA did not alter the proliferative activity and IL-2 expression in the sham group range, as significant differences were also noted between the sepsis with BoxA group and the sham group." (PMID 30881224, 2019). "The AUCs for IL-2, IL-6 and IL-10 were 0.901 (95% CI, 0.866 to 0.930), 0.860 (95% CI, 0.821 to 0.894), 0.888 (95% CI, 0.851 to 0.918), respectively, indicating that IL-2, IL-6 and IL-10 were effective biomarkers to rule out sepsis and intracranial infection." (PMID 24887408, 2014). "The AUCs for IL-2, IL-6, IL-10 and CRP were 0.901 (95% CI, 0.866 to 0.930), 0.86 (95% CI, 0.821 to 0.894), 0.888 (95% CI, 0.851 to 0.918) and 0.848 (95% CI, 0.807 to 0.883) respectively, indicating that IL-2, IL-6 and IL-10 were effective biomarkers to rule out sepsis and intracranial infection." (PMID 24887408, 2014). "It is plausible that the decrease in IL-2 gene expression which we observed in patients with gram negative infection and sepsis may reflect a failure of T cell activation." (PMID 21711552, 2011). "Numerous biomarkers, such as interleukin 6 (IL 6), interleukin 2 (IL 2), CRP, and PCT, have been extensively studied in an effort to distinguish infections from non-infectious causes of fever in sepsis patients, which could potentially aid in optimizing the use of antibiotics." (PMID 38681106, 2024). "In agreement with data presented before, sepsis did not affect the fold change in gene expression of TRM effector cytokines, IFN-γ and IL-2, in the left ear." (PMID 28910403, 2017). "Our observation that hMSCs can suppress IL-2, IL-6 and TNF but not IFNγ is consistent with a previous finding in which administration of mMSCs reduced serum levels of IL-6 and TNF but not that of IFNγ in a cecal ligation and puncture model of sepsis." (PMID 24423010, 2014).
Sepsis (continued). "Moreover, serum levels of IL-1β, IL-2, IL-4, IL-10, IL-17, IFN-α, IFN-β and IFN-γ were not elevated in severe sepsis survivors compared with sham-operated control mice (data not shown)." (PMID 23808943, 2013).
neuroblastoma (115 papers, 1993 to 2026). Neuroblastoma (NB) is the most common solid, extracranial childhood tumor. "In the largest reported series (n = 1,183) of high-risk neuroblastoma (HR-NB) patients treated with dinutuximab, isotretinoin, IL-2, and GM-CSF (sargramostim) post-consolidation/maintenance, the 5-year event-free survival rate only reached 61%." (PMID 40718780, 2025). "The treatment of neuroblastoma patients with cytokines (IL-2 and GM-CSF) is associated with a strong increase of activated CD64+ granulocytes and monocytes." (PMID 40805207, 2025). "For example, immunotherapy with ch14.18, GM-CSF, and interleukin-2 was associated with a significantly improved outcome as compared with standard therapy in patients with high-risk neuroblastoma." (PMID 37512574, 2023). "In a non-randomized study, anti-GD2 antibody hu14.18K322A was combined with six cycles of the COG induction chemotherapy and granulocyte-macrophage colony-stimulating factor and low-dose interleukin-2 (IL-2) in newly diagnosed high-risk neuroblastoma patients." (PMID 36765861, 2023). "Immunotherapy with IL-2 and GM-CSF has significantly improved survival in children with high-risk neuroblastoma." (PMID 37081982, 2023). "The European Medicines Agency (EMA) approved it for pediatric use in 2017 for the post-consolidation treatment of patients with high-risk neuroblastoma in combination with isotretinoin and IL-2." (PMID 37509390, 2023). "Currently, a combination of Dinutuximab beta and intravenous IL2 administration is also being tested for high-risk neuroblastoma patients in Phase III trial (NCT01704716)." (PMID 37509200, 2023). "Immunotherapy with an anti-GD2 antibody with GM-CSF, interleukin-2, and isotretinoin was associated with a significantly improved outcome compared with standard therapy in patients with high-risk neuroblastoma." (PMID 36171902, 2022). "Another clinical trial has demonstrated significantly improved outcomes in patients with high-risk neuroblastoma after the combined treatment with ch14.18 antibody to isotretinoin and IL2 or granulocyte macrophage-colony stimulating factor (GM-CSF)." (PMID 32560387, 2020). "Patients with high-risk neuroblastoma treated with continuous long-term infusion of anti-GD2 antibody dinutuximab beta (DB) in combination with IL-2 show an acceptable safety profile." (PMID 33392114, 2020). "IL-2, a human recombinant product, effective in the treatment of a variety of malignancies including neuroblastoma, has been associated with important treatment-related clinical toxic effects." (PMID 29900007, 2018). "Dinutuximab, a chimeric human-mouse monoclonal antibody against GD2, was approved in 2015 to be used together with GM-CSF, IL2 and 13-cis retinoic acid to treat high risk neuroblastoma." (PMID 29156825, 2017). "In pediatrics, IL-2 has been used most notably for the treatment of high-risk neuroblastoma in combination with an anti-GD2 monoclonal antibody (mAb) and granulocyte-macrophage colony-stimulating factor (GM-CSF)." (PMID 26301204, 2015). "Treatment for children with high-risk neuroblastoma with anti-disialoganglioside mAb ch14.18, IL-2, and GM-CSF plus 13-cis-retinoic acid after myeloablative chemotherapy improves survival, but 40 % of patients still relapse during or after this therapy." (PMID 23982484, 2013). "The fibroblast vaccine consisted of an embryonic fibroblast cell line, AJ3.1, transfected with plasmids encoding IL-2 and IL-12, while the tumour cell vaccine comprised syngeneic Neuro-2A neuroblastoma cells transfected with the same plasmids." (PMID 17595664, 2007). "As a result, scholars validated the tumor suppressive effect of IL-15 on PDX models, and they demonstrated that the replacement of IL-2 with IL-15 was associated with significant tumor regression in vivo, supporting clinical trials of IL-15 for pediatric neuroblastoma." (PMID 37081982, 2023).
neuroblastoma (continued). "A randomized phase III trial was conducted by the Children Oncology Group (COG), showing that anti-GD2 ch14.18 (dinutuximab) plus GM-CSF and IL-2 could enhance the survival of children with high-risk neuroblastoma." (PMID 35327550, 2022). "Combinational usage of Dinutuximab and interleukin 2 (IL-2), granulosa cell macrophage colony-stimulating factor (GM-CSF), and isotretinoin have been found to significantly increase the survival of patients diagnosed with high-risk neuroblastoma." (PMID 36237324, 2022). "This clinical trial progression culminated in a recently completed phase III randomized study of cisRA together with ch14.18, IL-2, and GM-CSF vs. cisRA only for patients with high-risk neuroblastoma who had a clinical response to induction therapy and myeloablative consolidation therapy/AHSCT." (PMID 34796286, 2021). "Hence, these findings indicate that anti-GD2 therapy combined with GM-CSF and IL-2 will improve the survival of patients with high-risk neuroblastoma." (PMID 34796286, 2021). "Further, the combination of the chimeric antibody ch14.18 dinutuximab with the granulocyte–macrophage colony-stimulating factor (GM-CSF) or interleukin-2 (IL2) has demonstrated significantly improved 2-year event-free survival in high-risk neuroblastoma patients." (PMID 34367149, 2021). "In another study, it was shown that low expression of CD4+/CD25+/CD127- T reg cells and high levels of IFNγ are associated with improved survival of neuroblastoma patients which are treated with anti-GD2 antibody ch14.18/CHO in combination with interleukin 2 (IL2)." (PMID 32722460, 2020). "This study shows that omitting IL-2 from immunotherapy with DB allows reduced co-medication and hospitalization time and therefore results in improved quality of life in patients with high-risk neuroblastoma." (PMID 33392114, 2020). "Similarly, a randomized phase III trial conducted by the Children’s Oncology Group (COG) showed that the combination of anti-GD2 ch14.18 (dinutuximab) with GM-CSF and IL-2 could improve survival rates among children with high-risk neuroblastoma." (PMID 38927907, 2024). "A randomized trial has demonstrated that therapy with an anti-GD2 antibody, interleukin-2 (IL-2), granulocyte-macrophage colony-stimulating factor (GM-CSF) and isotretinoin in the maintenance setting improves outcomes of patients with high-risk neuroblastoma (HR-NB)." (PMID 37813959, 2023). "Patients with high-risk neuroblastoma who were treated with ch14.18 in combination with IL-2 and GM-CSF with indication that the chemokine CXCL9 was somewhat prognostic at pretreatment, suggesting recruitment of immune effector cells like NK cells to the tumor could be beneficial." (PMID 34199783, 2021). "High-risk neuroblastoma (NB) remains a major therapeutic challenge despite the recent advent of disialoganglioside (GD2)-antibody treatment combined with interleukin (IL)-2 and granulocyte monocyte-colony stimulating factor (GM-CSF)." (PMID 27716850, 2016). "The oldest, registered under NCT01404702, commenced in 2011 and investigated the stimulating effect of zoledronic acid (ZOL) therapy combined with interleukin-2 (IL-2) on γδ T cells capable of killing neuroblastoma cells in a pediatric group." (PMID 40276509, 2025). "Anti-GD2 monoclonal antibodies have been used in combination with various administration regimens, including chemotherapy, cytokines like IL-2 and granulocyte–macrophage colony-stimulating factor (GM-CSF), or allogeneic NK cells in neuroblastoma treatment." (PMID 38927907, 2024). "This phase I trial investigates the maximum tolerated dose of Ch14.18 in combination with sargramostim and interleukin-2 in children with neuroblastoma who have completed bone marrow or peripheral blood stem cell transplantation." (PMID 39620227, 2024).